ALB (albumin)
Diseases named in the same sentence as ALB in open-access papers (continued):
Sharing a sentence is not in itself a finding about the gene and the disease.
diabetes (continued). "The National Institute for Clinical Excellence (UK) and the Standards of Medical Care in Diabetes from ADA both recommend kidney care for all people with type 2 diabetes that includes measuring ACR or albumin levels annually." (PMID 34135862, 2021). "In diabetes, the levels of these hormones are dysregulated, thereby leading to abnormal albumin metabolism." (PMID 32681438, 2021). "Multivariate Cox regression analysis showed that log-transformed BNP levels, serum albumin and diabetes status were predictors of mortality in hemodialysis patients." (PMID 34465266, 2021). "Another smaller randomized clinical trial involving 19 patients with obesity and diabetes and 19 medical controls showed insignificant reduction of urine albumin–creatinine ratio (− 1.0 vs. 0.0 mg/g, P = 0.96)." (PMID 32683637, 2021). "An increase in oxidized serum ALB level has also been observed in diabetes mellitus, but it has been less investigated compared with liver diseases and renal failures." (PMID 33804859, 2021). "Age, duration of diabetes, treatment for diabetes, serum creatinine level, eGFR, and urine albumin-to-creatinine ratio (ACR) were significantly correlated with serum CMW level." (PMID 33479412, 2021). "Glycation of albumin usually is between 10 and 16%, but it is substantially higher in diabetes patients, between 16 and 40%." (PMID 34698244, 2021). "The highest TC/HDL-C group had the highest body mass index, percentage of diabetes and serum albumin level." (PMID 35011019, 2021). "Patients with other or secondary types of diabetes mellitus showed lower blood pressure, higher eGFR, lower urinary albumin, higher LDL-cholesterol and lower HbA1c compared to type 1 and type 2 diabetes patients." (PMID 34134677, 2021). "Where R = 4.046703 + 0.065109 LA – 0.174490 albumin – 2.290462 the type of Af + 0.004854 time – 0.536535 hypertension + 0.485112 diabetes + 0.482281CHD." (PMID 35155619, 2021). "A recent study also showed that in diabetes patients, BTMs are correlated with urine albumin to creatinine ratio, an indicator of nephropathy." (PMID 33505536, 2021). "Albuminuria is a biomarker in the diagnosis of kidney disease which is due to the presence of high albumin in the urine and is one of the complications of diabetes." (PMID 34712427, 2021). "The age, BMI, the proportion of patients with diabetes mellitus, proportion of used phosphate binders, blood hemoglobin, serum albumin, triglycerides, total cholesterol, hs-CRP, phosphorus, and Kt/V differed among the three groups." (PMID 33781171, 2021). "Conversely, lymphocytes, creatinine, albumin, troponin T, Pro-BNP, procalcitonin, ferritin, and IL-6 were found to have more impact in subjects with pre-existing diabetes than in those with COVID-associated hyperglycaemia." (PMID 34439986, 2021). "In patients with type 2 diabetes mellitus, renal morphologic changes are more heterogeneous, and diabetic glomerulopathy is less severe than in patients with type 1 diabetes mellitus with similar urinary albumin levels." (PMID 34993041, 2021). "The major plasma protein albumin can influence platelet function as well as atherogenesis and thrombosis in diabetes and other conditions." (PMID 34078390, 2021). "Another large randomized controlled study, the Membrane Permeability Outcome (MPO) study, showed that high-flux dialyzers were associated with significantly better survival than low-flux dialyzers in patients with diabetes or serum albumin levels <4.0 g/dL." (PMID 34513892, 2021). "The results in the present study of albumin association to increased adhesion solely in T2D patients can be an effect of an impaired regulating effect of albumin on platelets from diabetes patients." (PMID 34078390, 2021). "Host status, blood glucose level/diabetes, albumin levels/nutritional state, age, and body mass index are just a few of the risk factors that contribute to increased risk of chronic wound infection." (PMID 34583720, 2021).
diabetes (continued). "Our animal model satisfactorily demonstrated the key features of type 2 pre-diabetes, including a > 40% increase in body weight, higher blood glucose levels, an increased albumin-to-creatine ratio, and increased renal hypertrophy." (PMID 35008648, 2021). "After adjustment for duration of diabetes, history of cardiovascular disease and serum albumin, ox-LDL remained a significant effect modifier of the association between proteinuria and eGFR decline over time (p = 0.04)." (PMID 34072583, 2021). "An observational study of 101 patients with obesity and diabetes showed decrease in urine albumin–creatinine ratio from a median of 80–30 mg/g after bariatric surgery." (PMID 32683637, 2021). "The fractional catabolic rate of albumin is another important regulatory factor of albumin concentration in pathophysiologic states such as diabetes." (PMID 32681438, 2021). "Then, once diabetes and obesity have been confirmed, it was demonstrated that diabetic and obese rats presented higher levels of blood total protein and albumin." (PMID 34447317, 2021). "Patients in the Suture group had disproportionately higher rates of diabetes, femoral vein placement, and bacteremia in the 3 months before catheterization, as well as lower average Hb and serum albumin levels." (PMID 34741127, 2021). "As albumin increased, the proportion of people with normoglycemia significantly increased, while both the proportion of people with pre-diabetes and diabetes decreased (P < 0.001 for the trend)." (PMID 34055818, 2021). "Authors concluded that advanced age, together with hypertension, diabetes, increased LDL cholesterol, blood urea nitrogen, and decreased albumin, among others, were factors associated with COVID-19 mortality." (PMID 34068930, 2021). "Glycated albumin makes a significant contribution to the pathogenesis of diabetes and other diseases." (PMID 34638659, 2021). "A 2 g/L increase in albumin reduced the odds of HbA1c-defined dysglycemia, diabetes, and poor glycemia control by 12% to 36%, after adjustment for all possible confounders." (PMID 34055818, 2021). "In alloxan-induced diabetic rabbits, low doses of lipoic acid significantly lowered the concentration of urine albumin, ameliorated oxidative stress and renal injury, so the agent proved to be effective in the treatment of diabetes and DN." (PMID 34465338, 2021). "In our experiment model of early stage diabetes, we have noticed not only significant changes in the urinary excretion of albumin in diabetic rats but also in normoglycemic rats, both treated with suramin." (PMID 33635529, 2021). "Urinary creatinine, albumin, and protein concentration were significantly increased as diabetes progressed." (PMID 33922243, 2021). "Type 2 diabetic patients need to be screened for nephropathy by assessing urinary albumin at the time of diagnosis of diabetes." (PMID 34993041, 2021). "Patients with high LSM had significantly higher markers of liver injury (e.g. liver enzymes), lower albumin and platelets, higher BMI and were more likely to have metabolic syndrome and diabetes." (PMID 33536476, 2021). "Univariate Cox regression analysis revealed that factors including the age of the patient at catheter placement, serum albumin level, having diabetes as the primary disease and the place of residence were associated with the overall survival of the patients." (PMID 34233593, 2021). "The top eight important risk factors for DFU onset were plasma fibrinogen, neutrophil percentage and hemoglobin levels in whole blood, stroke, estimated glomerular filtration rate, age, duration of diabetes, and serum albumin levels." (PMID 34465375, 2021). "The formula for nonalcoholic fatty liver disease fibrosis score includes age, body mass index, impaired fasting glycemia or diabetes, the aspartate aminotransferase to alanine aminotransferase ratio, platelets, and albumin." (PMID 34463983, 2021).
diabetes (continued). "Using logistic regression analysis, the odds ratio was not statistically significant for the prediction of macrovascular events after full-adjusting for age, sex, diabetes, serum albumin, cholesterol, and triglyceride." (PMID 33801029, 2021). "It was also determined that the proportion of people with diabetes and pre-diabetes as defined by HbA1c decreased as albumin level increased, while the proportion of people with normoglycemia as defined by HbA1c changed inversely." (PMID 34055818, 2021). "Gender, race, diabetes,CAD, RD, serum P, PTH, and albumin were associated with cardiovascular mortality byunivariate analysis." (PMID 33576763, 2021). "Statistical significance remained after further adjusting for diabetes and hypertension (OR, 1.63; 95% CIs, 1.11–2.38, P = 0.012), and for serum albumin and hemoglobin (OR 1.52; 95% CIs 1.02–2.28, P = 0.042)." (PMID 34531464, 2021). "Data were collected on preoperative serum albumin, BMI, diabetes, and tobacco use as well as postoperative infections, readmissions, complications, and mortality." (PMID 34277906, 2021). "Albumin, as an exogenous or endogenous carrier protein for treating various diseases—primarily cancer, rheumatoid arthritis, diabetes and hepatitis—has demonstrated its potential in the form of products and numerous clinical trials." (PMID 34771316, 2021). "To examine the effects of miR-379 loss on kidney function, we measured albumin and creatinine levels in 24 h urine samples collected from control and STZ-injected diabetic WT and miR-379KO mice at 6 and 24 weeks after diabetes onset." (PMID 33398021, 2021). "The possible explanations for low KPS cluster are older age, more prevalent with diabetes and lower serum albumin levels after abstracting from our dataset." (PMID 33349082, 2021). "The anemia group also had a higher prevalence of diabetes mellitus, and lower serum albumin levels and eGFR than the control group." (PMID 33478025, 2021). "Cox proportional hazards regression models with adjustments for age, sex, BMI, smoking satus, alcohol use, LDL-C, HDL-C, systolic BP, HbA1c, duration of diabetes, urinary albumin to creatinine ratio, prior CVD, prior cancer, medications at enrolment." (PMID 33763024, 2021). "Our experimental results revealed that albumin, hemoglobin, total protein (TP), expectoration, diarrhea, soreness, fever, cough, diabetes, ARDS, and shock were highly related to the recovery-time prediction, which was consistent with prior studies." (PMID 34400751, 2021). "A low fibrinogen level was associated with the development of AKI in the entire study population after adjusting for preoperative factors, including the MELD score, diabetes mellitus, BMI, albumin level, and PS." (PMID 34086798, 2021). "Another interesting finding was that p.Lys68Gln carriers had a higher BMI, hypoinsulinemia, worse diabetes control and an increased urine albumin/creatinine ratio compared to the p.Arg252His carriers, suggesting an allelic heterogeneity." (PMID 34193236, 2021). "From the clinical data statistically compared in our study, male gender, diabetes, neoadjuvant therapy, low albumin, and distance from the anal margin ≤ 5 cm are all statistically significant risk factors for anastomotic leakage." (PMID 34456630, 2021). "A recent study has shown that in diabetes, BTMs correlate with urine albumin to creatinine ratio, an indicator of early-stage nephropathy." (PMID 33505536, 2021). "The authors concluded that prevalence of malnutrition was high, and nutritional support should be strengthened during treatment, especially for those with diabetes, low calf circumference, or low albumin." (PMID 33919840, 2021). "DN is characterized by pathological albumin excretion or albumin/creatinine ratio in the urine of patients with diabetes and a decrease in the glomerular filtration rate." (PMID 33959621, 2021).
diabetes (continued). "The diabetics were divided into threesubgroups according to 24-hour urine albumin: normal to mildly increased(A1) (n=51), moderately increased (A2) (n=25), severely increased (A3)(n=25) albuminuria." (PMID 33599678, 2021). "The urinary albumin-to-creatinine ratio increased rapidly to an average of 93 mg/g three weeks after diabetes induction, which was five-fold higher than their baseline values." (PMID 34884571, 2021). "Significant differences in diabetes, total protein (TP), albumin (ALB), and monocyte were found between these two groups (p < 0.05)." (PMID 34589441, 2021). "Existing studies have reported many risk factors for anastomotic leakage, such as male gender, neoadjuvant CRT, anastomotic position, diabetes, and low albumin." (PMID 34456630, 2021). "The association was independent of age, gender, race/ethnicity, education levels, BMI, diabetes history, smoking status, alcohol consumption, sodium intake, triglycerides, total cholesterol levels, albumin, eGFR, and serum phosphorus." (PMID 34912855, 2021). "Alternative methods for diabetes management, such as fructosamine, glycosylated albumin and device-based continuous glucose monitoring, are discussed." (PMID 32913038, 2021). "These agents are recommended for adults with diabetes and a urine albumin-to-creatinine ratio (ACR) of at least 30 mg per 24 h or any adult with a urine ACR of at least 300 mg per 24 h." (PMID 34068380, 2021). "Diabetic nephropathy is defined as the appearance of chronic kidney disease in diabetes mellitus, accompanied by continuous elevation of urinary albumin excretion or a persistent reduction in estimated glomerular filtration rates." (PMID 34775979, 2021). "Compared to type 2 diabetes patients, patients with type 1 diabetes mellitus had higher percentages of missing data on BMI, blood pressure, eGFR, urinary albumin and cholesterol." (PMID 34134677, 2021). "We included the following factors as explanatory variables: history of diabetes mellitus, body mass index at hospitalization, serum albumin level at hospitalization, use of a nasogastric feeding tube, and treatment with HET." (PMID 34050227, 2021). "This relationship was particularly apparent in male participants, those aged <65 years, those with a duration of diabetes of <10 years, and those with a urinary albumin − to − creatinine ratio (UACR) < 30 mg/g." (PMID 34458375, 2021). "With lambda of 0.125, 6 key factors were identified to be of great significance to the prognosis of patients with pancreatic ductal adenocarcinoma, including chemotherapy, TNM stage, diabetes, albumin, lymphocyte count and CA19-9." (PMID 34136406, 2021). "Age, diabetes mellitus, ability to perform IADL, lower haemoglobin level, higher urea level, and lower albumin level were associated with frailty based on both scales." (PMID 34394346, 2021). "Similar to the reports above, comparisons in the present study showed that PJP+ IIM patients had been receiving higher doses of corticosteroids and had a higher prevalence of diabetes, lower albumin level, and low CD4+ T cell counts." (PMID 34481528, 2021). "Compared to younger patients, this group had lower hemoglobin and serum albumin levels, a higher incidence of nephrotic-range proteinuria, and higher prevalences of hypertension and diabetes." (PMID 33035278, 2020). "The significant risk factors for low ionized calcium levels were higher age, CRP, and iPTH; male sex; lower eGFR, BMI, albumin levels; and diabetes (P < 0.05)." (PMID 32157180, 2020). "A mono-segmented sequential injection lab-at-valve (SI-LAV) system for the determination of albumin, glucose, and creatinine, three key biomarkers in diabetes screening and diagnosis, was developed as a single system for multi-analyte analysis." (PMID 32260353, 2020). "Studies in animals have suggested that bovine serum albumin (BSA) is the milk protein responsible of the development of diabetes." (PMID 32670194, 2020).
diabetes (continued). "Reduced albumin-adjusted plasma-free thiol levels (OR (odds ratio) = 0.87), increased Acute Physiology And Chronic Health Evaluation (APACHE) IV (OR = 1.03), and diabetes mellitus (OR = 2.68) were independently associated with an increased risk of AKI." (PMID 33207555, 2020). "Cubic spline regression analysis was used to examine the relationship between HGS or LMI values and mortality, and explore the cut-off points after adjusting for age, diabetes, cardiovascular disease and serum albumin in the development cohort." (PMID 33062032, 2020). "Patients in the lowest albumin tertile (<3.8 g/dL) were older and more likely to have lower body mass index, lower systolic blood pressure, and more frequent histories of diabetes mellitus, old myocardial infarction, and malignancy." (PMID 32872477, 2020). "After multivariate adjustment for age, eGFR, serum albumin, diabetes mellitus, comorbidity, Adragao Score > 3 and serum phosphate, the presence of VF (HR 1.983, 95% CI 1.009‒3.898, p = 0.047) was and independent predictor of all-cause mortality." (PMID 32466297, 2020). "The Best-fit Risk Score included urinary albumin-to-creatinine ratio, SBP, C-reactive protein, triglyceride, sex, education, and diabetes." (PMID 32252667, 2020). "In the multivariable analysis for the adjustment with Ln-HD duration, mean blood pressure, pH, serum albumin, and presence of diabetes mellitus, a linear relationship was demonstrated between the two variables (p for linearity = 0.79)." (PMID 32776946, 2020). "Compared with the individuals with diabetes in the NDR group, the SUA, homocysteine, TC, LDL-c and urinary albumin levels of individuals with diabetes in the NPDR and PDR group were significantly higher (P < 0.05)." (PMID 33256661, 2020). "After multivariate adjustment for age, MDRD, albumin, diabetes mellitus, comorbidity, Adragao Score > 3 and serum phosphate, the presence of VF (HR 1.983, 95% CI 1.009‒3.898, p = 0.047) were an independent predictor of all-cause mortality." (PMID 32466297, 2020). "After adjusting for age, dialysis vintage, education, diabetes, serum albumin, hs-CRP, hyponatremia and mean arterial pressure, total Kt/V was only independently associated with delayed memory (P = 0.015)." (PMID 31643008, 2020). "Diabetic kidney disease (DKD) is one of the most common microvascular complications of diabetes mellitus (DM) characterized by an increased urinary albumin excretion rate and declined renal function." (PMID 32685558, 2020). "The univariate COX proportional hazards regression analysis showed that age, diabetes, glucose, albumin, total cholesterol, creatinine, D-Dimer, LVEF and visfatin were associated with the time to MACEs." (PMID 32503436, 2020). "We found decreased SIRT1 levels in patients with increased urinary albumin excretion (UAE), the lowest with diabetes presence, and a strong association with UAE, discriminating incipient renal damage." (PMID 32887498, 2020). "On multivariate analysis, a higher dose of corticosteroid, a lower level of serum albumin, the experience of hospitalization, and comorbidities, including respiratory disease, eye disease, and diabetes, remained significant." (PMID 32793235, 2020). "The American Diabetes Association recommends spot urinary albumin-to-creatinine ratio, serum creatinine and estimated glomerular filtration rates evaluations at baseline and then annually." (PMID 32727401, 2020). "The risk factors on graft and patient survival were race, age, gender, BMI, MELD score, presence of diabetes, albumin, encephalopathy, portal vein thrombosis, poor performance status and disease etiology." (PMID 33382811, 2020). "In T2D, FKBPL was negatively correlated with fasting blood glucose, HbA1c and diastolic blood pressure (DBP), and positively correlated with age, known diabetes duration, waist/hip ratio, urinary albumin/creatinine ratio (ACR) and fasting C-peptide." (PMID 33303872, 2020).